WT1 (WT1 transcription factor)
Diseases named in the same sentence as WT1 in open-access papers (continued):
Sharing a sentence is not in itself a finding about the gene and the disease.
acute myeloid leukemia (continued). "Since the number of copies of WT1 mRNA (WT1cn) correlates well with the burden of acute myeloid leukemia (AML), WT1cn has been used as a reliable marker of residual AML cells." (PMID 36467821, 2022). "The quinolinate phosphoribosyltransferase (QPRT) gene was shown to be activated by Wilms’ tumor gene 1 (WT1) resulting in expanded antiapoptotic properties in acute myeloid leukemia and acting as an oncogenic protein." (PMID 36500178, 2022). "The second top both DMR and DVR in our study (including 41 CpG sites) was annotated to WT1, an oncogene in acute myeloid leukemia." (PMID 33632303, 2021). "In acute myeloid leukemia (AML) TET2 mutations have been observed to be mutually exclusive with IDH1, IDH2, and WT1 mutations, all of them showing a similar impact on the transcription profile." (PMID 33805247, 2021). "Our study supported the oncogenic role of WT1 in myeloid leukemia, and the highlight of this work is the discovery of new WT1 target genes, IL-2, IL-2RB, and IL-2RG, which are likely involved in WT1-mediated leukemogenesis in acute myelogenous leukemia." (PMID 33110919, 2020). "It was also regarded as a key element in acute myeloid leukemia, and WT1 overexpression was an independent positive prognostic factor in adult B-cell acute lymphoblastic leukemia patients." (PMID 32224871, 2020). "Overexpression of Wilms’ tumor-1 (WT1) transcription factor facilitates proliferation in acute myeloid leukemia (AML)." (PMID 32580769, 2020). "In this study, we reported the accomplishment in the production of lentiviral-based RNAi which effectively inhibited WT1 expression in acute myeloid leukemia cells, K562." (PMID 33110919, 2020). "The usefulness of WT1 quantitative assessment q-PCR as a marker for measurable residual disease (MRD) detection in acute myeloid leukemia was demonstrated years ago." (PMID 31067725, 2019). "The publication “Wilm’s tumor-1 (WT1) rs16754 Polymorphism and Clinical Outcome in Acute Myeloid Leukemia” was very interesting." (PMID 30520285, 2019). "For example, in acute myeloid leukemia derived cell lines, AWT1 (a transcript from an alternative promoter of the WT1 (Wilms tumor 1) gene) is highly expressed despite the hypermethylation of its promoter." (PMID 31181625, 2019). "Wilms' tumor gene 1 (WT1) expression is a well-known predictor for relapse in acute myeloid leukemia." (PMID 28114959, 2017). "We formerly demonstrated that vaccination with Wilms’ tumor 1 (WT1)-loaded autologous monocyte-derived dendritic cells (mo-DCs) can be a well-tolerated effective treatment in acute myeloid leukemia (AML) patients." (PMID 27659531, 2016). "We performed a systematic review of data from nine clinical trials of WT1 peptide vaccination in patients with myelodysplastic syndromes and/or acute myeloid leukemia (MDS/AML), published between 2004 and 2012." (PMID 25699052, 2015). "This review, we will summarize the immunologic and clinical results of WT1 peptide vaccination approaches in patients with myelodysplastic syndromes and/or acute myeloid leukemia (MDS/AML)." (PMID 25699052, 2015). "Recently, clinical trials of WT1 peptide-based immunotherapy have been conducted in various malignancies including renal cell carcinoma, multiple myeloma, acute myeloid leukemia, lung cancer, and MDS 42–47." (PMID 24715586, 2014). "Wilms' tumor gene 1 (WT1), located on the short arm of chromosome 11, is expressed in most patients with acute myeloid leukemia (AML) or lymphocytic leukemia (ALL)." (PMID 23936694, 2013). "WT1 mutations have also been demonstrated in approximately 10% of T-acute lymphoblastic leukaemia (T-ALL) and acute myeloid leukaemia (AML) patients." (PMID 23484026, 2013). "Here, we analyzed 10 HLA-A2 positive patients with acute myeloid leukemia (AML) for loss or mutations of the WT1 epitope or epitope flanking sequences that may abolish proper T cell recognition or epitope presentation." (PMID 20092642, 2010).
acute myeloid leukemia (continued). "Recent studies have shown that WT1 plays an important role in the progression of disease and indicates a poorer prognosis of human malignancies such as acute myeloid leukemia and breast cancer." (PMID 16606472, 2006). "Wilm’s tumor 1 (WT1), a zinc-finger transcription factor and an epigenetic modifier, is frequently overexpressed in several hematologic disorders and solid tumors, and it has been proposed as diagnostic and prognostic marker of acute myeloid leukemia (AML) and myelodysplastic syndrome (MDS)." (PMID 33917307, 2021). "Somatic mutations in Wilms' tumor 1 (WT1) and tet methylcytosine dioxygenase 2 (TET2) genes were separately perceived as contributors to hematopoietic disorders and usually thought to have a mutually exclusive effect in acute myeloid leukemia (AML)." (PMID 34120595, 2021). "WT1, a transcription factor and regulator of podocyte differentiation and homeostasis, is aberrantly expressed in various types of human cancers, such as uterine cancer and acute myeloid leukemia." (PMID 32322310, 2020). "We conclude that co-occurrence of WT1 mutation, NUP98-NSD1, and FLT3-ITD with an AR ≥0.4 as triple or double mutations still predicts dismal response to contemporary first- and second-line treatment for pediatric acute myeloid leukemia." (PMID 31467532, 2019). "Another oncogene, WT1, is also overexpressed in the majority of acute myeloid leukemia patients." (PMID 31396278, 2019). "WT1 is over-expressed in numerous hematological malignancies like acute myeloid leukemia (AML), as well as in many solid malignancies such as ovarian cancer, thus the created WT1 TCRm CAR T-cell approach allows for the application of a single CAR to a wider array of malignancies 106-108." (PMID 31695801, 2019). "The Wilms tumor gene 1 (WT1) is a transcription factor that acts as an oncogene in acute myeloid leukemia, and a recent Chip-Seq investigation has revealed that binding of the WT1-KTS isoform in leukemic cells is correlated to active transcription of numerous genes." (PMID 29046813, 2017). "Finally, we found a significant inverse correlation between miR-15a or miR-16-1 expression and WT1 protein levels in primary acute myeloid leukemia (AML) blasts and normal controls." (PMID 22133358, 2011). "NCT00965224 employed dendritic cells (DCs) electroporated with WT1 mRNA in patients with acute myeloid leukemia (AML) and included MM patients in its exploratory scope." (PMID 41596492, 2026). "Most of these patients presented with synchronous bilateral tumors, but three had metachronous bilateral disease (intervals of 4.3 to 7 years), and one (QLH) developed a WT1-based secondary AML (acute myeloid leukemia)." (PMID 40340749, 2025). "Increased WT1 mRNA levels are pervasive in acute myeloid leukemia (AML), and this marker has been used to assess the leukemic compartment size after chemotherapy or hematopoietic cell transplants." (PMID 40613901, 2025). "A study in acute myeloid leukemia (AML) reported that TEG cells targeting Wilms’ tumor antigen (WT1) successfully controlled leukemia progression in patients without severe toxicity." (PMID 40226616, 2025). "NTLA-5001 is an investigational CRISPR/Cas9-engineered T-cell receptor (TCR)-T cell therapy in development for the treatment of all genetic subtypes of acute myeloid leukemia (AML) using a WT1-targeting TCR." (PMID 38424590, 2024). "During the treatment of 89 pediatric patients with Acute Myeloid Leukemia (AML) at the Hematology Department of Kunming Medical University’s Children’s Hospital from 2020 to 2023, three patients were identified to co-express the NUP98-NSD1, FLT3-ITD, and WT1 gene mutations." (PMID 39068406, 2024). "Similarly, hypoxia-mediated TET2 and TET3 upregulation promoted CpG island demethylation and induced Wilms’ tumor-1 (WT-1) protein expression in acute myeloid leukemia stem cells, which played an important role in regulating stem cell proliferation and differentiation." (PMID 38704599, 2024).
acute myeloid leukemia (continued). "Vaccination with DCs electroporated with mRNA encoding WT1 (NCT00965224) or WT1, PRAME, and CMVpp65 (NCT01734304) or CT7, MAGE-A3, and WT1 mRNA (NCT01995708) or WT1/PRAME (NCT02405338) mRNA was tested in acute myeloid leukemia (AML)." (PMID 36839944, 2023). "The aim of this study was to evaluate the role of WT1 expression after allogeneic stem cell transplantation (alloHSCT) in patients with acute myeloid leukemia (AML)." (PMID 36119469, 2022). "In a phase II clinical study (NCT00965224), patients with acute myeloid leukemia (AML) in remission were vaccinated with WT1 mRNA-electroporated DCs." (PMID 33858437, 2021). "Several studies reported the use of TCR-engineered T cells to treat patients including NY-ESO-1-directed tTCR and MAGE-A3-directed tTCR for multiple myeloma (MM), and WT1-directed tTCR for acute myeloid leukemia (AML)." (PMID 34650571, 2021). "Targeted NGS analysis performed at diagnosis and focused on acute myeloid leukemia driver genes is helpful since the presence of pathogenic mutants (IDH1 p.Arg132His, SRSF2 p.Pro95Thr, WT1 p.Cys393Ter in this study) could represent additional risk factors or opportunities for targeted therapy." (PMID 30848074, 2019). "The Wilms tumor 1 (WT1)-associated protein (WTAP) is upregulated in many tumors, including, acute myeloid leukemia (AML), where it plays an oncogenic role by interacting with different proteins involved in RNA processing and cell proliferation." (PMID 30038300, 2018). "Wilms’ tumor 1 (WT1) is a promising target of new immunotherapies for acute myeloid leukemia (AML) as well as for other cancers." (PMID 28321480, 2017). "We found that pure curcumin upregulated the expression of miR-15a/16-1 and downregulated the expression of WT1 in leukemic cells and primary acute myeloid leukemia (AML) cells." (PMID 22449094, 2012). "In comparison to normal PBMCs, WT1 mRNA was detected at higher levels in all 18 patients with acute leukemia (AML), including 3 patients with acute lymphoblastic leukemia (ALL) and 15 patients with acute myeloid leukemia (AML)." (PMID 19662212, 2007). "The resulting computational models were applied on an independent published dataset from acute myeloid leukemia (AML) patients, treated with hematopoietic stem cell transplantation, to track WT1-specific TCRs in silico." (PMID 39259326, 2025). "In the context of hematopoietic tumors, including acute myeloid leukemia (AML), WT1 has been identified as a potential marker for measurable residual disease (MRD) assessment." (PMID 39274359, 2024). "In this study, we observed that pediatric patients with acute myeloid leukemia (AML) exhibiting co-expression of NUP98-NSD1, FLT3-ITD, and WT1 in our cohort showed a lower response rate to chemotherapy." (PMID 39068406, 2024). "In 2018, another clinical study (NCT02770820) used WT1-specific central memory and infantile CD8+ TCR-T cells to treat acute myeloid leukemia." (PMID 37649123, 2023). "WT1-TCB promotes an efficient in vitro, ex vivo and in vivo killing of acute myelocytic leukemia cell lines and primary acute myelocytic leukemia." (PMID 35401191, 2022). "Wilms’ tumor 1 (WT1) protein is highly immunogenic and overexpressed in acute myeloid leukemia (AML), consequently ranked as a promising target for novel immunotherapeutic strategies." (PMID 35476127, 2022). "Sequential monitoring of Wilms’ tumor gene 1 (WT1) after allogeneic hematopoietic stem cell transplantation (allo-HSCT) could predict relapse in adult acute myeloid leukemia (AML)." (PMID 33740924, 2021).
acute myeloid leukemia (continued). "One (NCT03291444) combines a variety of CAR-T cells with Eps8 or WT1 peptide-loaded DCs against ALL, acute myeloid leukemia (AML), and myelodysplastic syndrome." (PMID 32429316, 2020). "Likewise, WT1 is overexpressed in 60 to 100% of patients with acute lymphoblastic leukemia (ALL) or acute myeloid leukemia (AML)." (PMID 30678050, 2019). "WT1, KRAS, NRAS mutations, FLT3 activation, or Myc trisomy, which are common genetic events in many other subsets of acute myeloid leukemia (AML), may be observed in APL patients." (PMID 29795382, 2018). "In most acute myeloid leukemia (AML) and acute lymphoid leukemia (ALL) blast cells, WT1 is highly expressed and correlated to poor clinical outcome." (PMID 29152069, 2017). "For example, the Wilms’ tumor 1 (WT1) gene is a regulating factor in cell proliferation, which is highly expressed in patients with acute myeloid leukemia." (PMID 27529277, 2016). "In breast and prostate cancers as well as in acute myeloid leukemia (AML) a correlation with WT1 expression has been observed, suggesting that PAX2 is a positive transcriptional regulator of WT1." (PMID 19467152, 2009). "In acute myeloid leukemia (AML), the WT1-targeting vaccine galinpepimut-S (GPS) achieved a median overall survival of >12 months versus 6 months in controls (REGAL phase III trial, NCT04229979), correlating with robust WT1-specific T-cell responses in 80% of patients." (PMID 40507941, 2025). "Although many studies have explored the prognostic value of WT1 expression in acute myeloid leukemia (AML), there is still a lack of research on the prognostic significance of WT1 expression in ALL, particularly in pediatric BCP-ALL." (PMID 38293695, 2023). "In WT1-transgenic mice with forced hematopoietic progenitor WT1 overexpression, rapid onset acute myeloid leukemia was induced by AML1-ETO fusion transduction, as opposed to the wild-type model, where transduction was insufficient to cause systemic disease." (PMID 35453662, 2022). "Concordantly, several TF were reported to interact with TET2, including Wilms Tumor 1 (WT1), which was found to recruit TET2 to its target genes in acute myeloid leukemia (AML) cells, or early B-cell factor 1 (EBF1), which was reported to interact with TET2 in IDH-mutant cancers." (PMID 33692344, 2021). "In acute myeloid leukemia (AML), WT1 could be a potential prognostic factor, marker for minimal residual disease and target of vaccination immunotherapy." (PMID 32244895, 2020). "We previously performed a phase I/II clinical trial to examine the safety of as well as the clinical and immunological responses to a WT1 HLA class I peptide vaccine for HLA-A*24:02-positive patients with myelodysplastic syndrome (MDS), acute myeloid leukemia (AML), and breast and lung cancers." (PMID 30430205, 2019). "We peptide-pulsed healthy donor and acute myeloid leukemia (AML) patient samples with VLDFAPPGA (VLD, WT137-45) and RMFPNAPYL (RMF, WT1126-134) peptides, then sequenced the WT1 dextramer-positive CD8 + T-cells with single-cell RNA + TCRαβ sequencing." (PMID 40847198, 2025). "Acute myeloid leukemia (AML) progression is significantly influenced by Feline McDonough Sarcoma (FMS)-like tyrosine kinase 3 (FLT3) signaling, while Wilms’ tumor 1 (WT1) serves as a key prognostic marker." (PMID 40361130, 2025). "Clinical trials of acute myeloid leukemia (AML), advanced pancreatic cancer, and MPM have been conducted with the WT1 peptide vaccine." (PMID 39116074, 2024).
acute myeloid leukemia (continued). "An aberrant WT1 expression was also observed in leukemic blasts of patients with acute lymphoblastic leukemia (ALL) of B- or T-lineages, acute myeloid leukemia (AML), chronic myeloid leukemia (CML) in blast crisis phase and myelodysplastic syndrome (MDS)." (PMID 37444601, 2023). "Also, the expression of GATA2 is significantly higher in AML compared to normal bone marrow, and recently Maaike Luesink and his colleagues found that high GATA2 expression was a poor prognostic marker in acute myeloid leukemia as well as other transcription factors EVI,WT1." (PMID 28114350, 2017). "In fact, a noncanonical G-to-A RNA editing was found in the WT1 transcript in nonprogenitor umbilical cord blood mononuclear cell samples (CBMCs), compared to acute myeloid leukemia (AML)." (PMID 37958449, 2023). "Additionally, WT1 expression has been identified and used as a potent transcriptional regulator and marker for myelodysplastic syndromes (MDS), acute myeloid leukemia (AML), and solid tumors, including breast carcinoma." (PMID 37513835, 2023).